APOE (apolipoprotein E)
Diseases named in the same sentence as APOE in open-access papers (continued):
Sharing a sentence is not in itself a finding about the gene and the disease.
dementia (continued). "Compared with APOE ɛ4 noncarriers with stable BMI, APOE ɛ4 carriers with large BMI loss (HR = 6.66, 95% CI 2.83−14.4) or gain (HR = 9.93, 95% CI 3.49–24.6) had higher dementia risk." (PMID 35921193, 2023). "Since the data obtained to date suggest that lipids are related to dementia and cognitive processes, the role of ApoE in the development of AD has been approached from the possible differences in lipid composition associated with the various alleles of this lipoprotein." (PMID 37444314, 2023). "APOE ε4 carriers showed higher dementia prevalence across all groups." (PMID 37371506, 2023). "Lower ApoE concentration was associated with worse cognitive function, but not with incident dementia." (PMID 37666928, 2023). "Stratified analyses showed that the joint association of CMD status and lifestyle with dementia risk was stronger in APOE ε4 noncarriers than in APOE ε4 carriers (Pinteraction <0.001)." (PMID 37876001, 2023). "In this study, an additional analysis was conducted to compare subjects in the ApoE ε4+ risk group who also had a family history of dementia with those in the ε4− group who did not have such a family history." (PMID 37509663, 2023). "One study of a predominantly non-Hispanic white sample (84.2%) found that among only APOE-ε4 allele carriers, a decline in BMI over 5 years was associated with conversion to mild cognitive impairment or dementia." (PMID 37731955, 2023). "The associations between PRS for type 2 diabetes and all-cause dementia as well as vascular dementia were stronger in the part of the population that did not have the APOE ε4 genotype." (PMID 37091584, 2023). "From our study, we conclude that the biological mechanism of weight loss in dementia is independent of APOE variants and other genetic factors that are linked to human longevity and BMI maintenance." (PMID 37628615, 2023). "The lack of established associations between ɛ4 and the KP in subjects with dementia does not exclude associations between APOE polymorphism and the KP in subjects with other disorders known to be associated with both APOE polymorphism and changes in the KP." (PMID 37895304, 2023). "In another study, the presence of APOE-ε4 and high levels of plasma p-tau 181 was associated with poor cognitive performance among 630 older individuals without dementia from the ADNI database, independent of the burden of β-amyloid pathology." (PMID 38115150, 2023). "But the association between elevated cystatin C and dementia was null for non-Hispanic White adults when APOE-ε4 was added to the model." (PMID 37323925, 2023). "In an equivalent analysis but using PRS 1–7 as exposure, the association between PRS 1–7 and all-cause dementia was, however, still non-significant in APOE ε4 carriers." (PMID 37091584, 2023). "In addition, the frequency of ApoE ε4 carriers is higher in both PD patients with dementia (PDD) than that in healthy controls." (PMID 36817952, 2023). "We have used their 11 cognitive test results and APOE genotype to determine, with the granular computing approach, that some of their normal patients might already have mild/very mild dementia or questionable impairment." (PMID 36850743, 2023). "Considering that B2M is a renal function indicator, previous studies have found that the APOE ε4 carrier status does not affect the decline in renal function as a marker for individual dementia risk." (PMID 37005674, 2023). "The APOE genotype also affects the age of onset and severity of stroke, and individuals with the APOE4 allele exhibit delayed recovery of verbal memory function and an increased risk of developing stroke-associated dementia." (PMID 37759556, 2023). "When stratifying for APOE ε4 status, associations between type 2 diabetes and all forms of dementia were stronger for non-carriers of APOE ε4." (PMID 37091584, 2023).
dementia (continued). "This longitudinal neuroimaging study aimed to identify cerebral regions whose atrophic trajectories contribute specifically to the transition from cognitive normal to dementia (CN2D) and outline the effect of APOE variants on cerebral atrophic trajectories during CN2D conversion." (PMID 37323144, 2023). "Moreover, APOE ε4 modulates a faster atrophic speed of the left hippocampus during dementia conversion." (PMID 37323144, 2023). "Adjusted for APOE-ɛ4, individuals with a PRS falling within the fourth quartile or tenth decile had a higher risk of dementia compared to those in the first quartile/decile: OR = 1.85 (95% CI = 1.25–2.74; p-value = 0.002) and OR = 2.27 (95% CI = 1.22–4.28; p-value = 0.01), respectively." (PMID 37834213, 2023). "In addition, the association between APOE-ε4 and cognition was also mediated through LBD, TDP-43, and CAA, but only among those with clinical dementia by the time of death." (PMID 38115150, 2023). "Lower plasma ApoE level has also been reported to be a risk factor for incident dementia and AD, independent of the APOE 2/3/4 polymorphism." (PMID 37666928, 2023). "Baseline low plasma ApoE level present in HDL lacking ApoC3 was a risk factor for incident dementia and worse cognitive function, but not in HDL having ApoC3." (PMID 37666928, 2023). "Among the proteins, APOE, CLU, CHL1, SLC1A3, RAB7A, and CST3 were related to the protein aggregation of misfolded proteins—causative agents and symptomatic of neurodegenerative diseases—such as α-synuclein in PD, and amyloid-β and tau in dementia." (PMID 36797805, 2023). "We propose that this mitochondria-to-APOE mechanism may operate in the pathogenesis of dementia, a proposition supported by our protein expression correlation studies in mouse Alzheimer’s brains and aging human brains." (PMID 37171075, 2023). "We thus genotyped the TOMM40 locus in our dementia population along with the APOE Ɛ4 status." (PMID 38028602, 2023). "Our findings suggested that vitamin D and grip strength may be imperative for estimating the risks of dementia, especially among APOE e4 genotype carries." (PMID 37246226, 2023). "Supporting the presence of non-AD dementias is the observation that APOE-ε4 genotype was associated with biomarker-positive AD." (PMID 37079306, 2023). "We aimed to increase the understanding of SVD and APOE genotype in dementia by studying a large memory clinic population, focusing on groups with a clinical continuum of increasing AD pathology, from subjective cognitive impairment (SCI) to mild cognitive impairment (MCI) and AD." (PMID 35912087, 2022). "The APOE ε4 and clinical dementia rating were statistically significant." (PMID 35328176, 2022). "Among APOE-ε4 carriers, especially non-fermented dairy intake associated with higher risk of dementia outcomes, and higher fish intake indicated better cognitive performance." (PMID 35217900, 2022). "Overall, our study shows that GRS for dementia generated from GWAS in European origin samples is associated with dementia diagnosis in those from diverse ancestries even when the GRS did not include APOE." (PMID 36477264, 2022). "From a series of longitudinal studies, associations between a composed lifestyle and dementia, AD, and cognition decline were suggested regardless of the APOE ε4 allele." (PMID 35619174, 2022). "White matter microstructural reductions have been shown in cognitively healthy individuals at an increased risk for AD (due to family history of dementia and having an APOE e4 allele) in the absence of medial temporal lobe atrophy." (PMID 36711200, 2022). "The cumulative incidence of dementia was twice as high in the ApoE-ɛ4 allele carriers than in the non-carriers, but this was not statistically significant." (PMID 35888143, 2022). "In contrast, we found a statistically significant interaction of APOE genotype with multimorbidity and dementia risk, finding stronger associations in noncarriers." (PMID 36125811, 2022).
dementia (continued). "The present study investigated the associations of EEG theta rhythm with delayed recall and the effects of ApoE genotype on these associations in elderly individuals without dementia." (PMID 35693343, 2022). "There are a number of potential covariates that might modify the risk of conversion to dementia in MCI subjects, including the APOE genotype status." (PMID 35805894, 2022). "It has also been suggested that diets rich in refined carbohydrates could promote dementia and AD through insulin resistance, especially among APOE ε4 carriers." (PMID 34632537, 2022). "A registry of individuals with a family history of dementia found that overall AC burden significantly interacted with APOE ε4 status only for the change in score for the delayed recall portion of the auditory verbal learning test (one of seven cognitive outcomes in the study)." (PMID 36506252, 2022). "Most of the positive associations between insomnia and dementia were not controlled for APOE-ε4, depressive status, and the use of hypnotic." (PMID 35057850, 2022). "In the process of follow-up of VCIND patients, it was found that APOE-ε4 gene carriers are at higher risk of developing dementia, and the progression-free survival of patients with the APOE-ε4 gene was significantly lower than that of noncarriers." (PMID 35317127, 2022). "Stronger association between glucosamine use and decreased risk of dementia was observed in participants without APOE ε4 carriers (HR = 0.81; 95% CI: 0.74–0.89) when compared to those with APOE ε4 carriers (HR = 0.93; 95% CI: 0.86–1.02)." (PMID 36514123, 2022). "The other major risk factors are apolipoprotein-E (APO-E) genes and a family history of dementia." (PMID 35621297, 2022). "The Rotterdam Study, which is a previous study on the relationship between lifestyle and the APOE allele, demonstrated that a healthy lifestyle including a healthy diet reduced the risk of dementia in individuals without the APOE ε4 allele." (PMID 36590218, 2022). "Many studies say that e4 alleles of the APOE gene can be a predisposition for dementia, but not necessarily." (PMID 35444165, 2022). "Self-reported sleep problems in dementia are characterized by very short or long sleep duration, low sleep efficiency, and excessive daytime sleepiness, especially among young-old people and APOE ε4 carriers." (PMID 34979998, 2022). "Thus, gaining an understanding of the mechanisms of apoE in disease pathogenesis will ultimately shed light on therapeutic strategies for the treatment of AD and related dementias." (PMID 36348357, 2022). "When stratifying by APOE-ε4 carrier status, the risk of incident dementia associated with multimorbidity was greater in noncarriers (HR, 1.96 [95% CI, 1.81-2.11]) and attenuated in carriers (HR, 1.39 [95% CI, 1.30-1.49])." (PMID 36125811, 2022). "APOE ε4 allele and male sex increased the risk of early onset by approximately 2 to 3 years in AD and mixed AD + LBD, while in pure LBD, depression and high education predicted a 5.5-year earlier onset of dementia." (PMID 35197840, 2022). "Moreover, hallucinations have been shown to be more common in patients with dementia with LBs carrying APOE ε4." (PMID 35741861, 2022). "This is consistent with APOE ε4 primarily, but not exclusively, influencing risk of dementia via Aβ deposition." (PMID 35410910, 2022). "In addition to AD, ApoE has also been reported to have an impact on dementia and synucleinopathy in Parkinson’s disease (PD) dementia and dementia with Lewy bodies as well as in mouse models of synucleinopathy." (PMID 36012187, 2022). "In addition, single-factor and multivariate logistic analysis of risk factors related to dementia survival rates also showed that WMV, WMH, Fazekas scores increased, and APOE-ε4 gene carriers were at higher risk of developing dementia (P < 0.05)." (PMID 35317127, 2022).
dementia (continued). "Of the 339,901 participants without the dementia incidents at baseline, the mean age was 57.29 (± 7.92) years, 42% were women, and 28% were APOE 4 allele carriers." (PMID 36199126, 2022). "In contrast, carriers of the APOE-3/3 genotype in haplotypes with the TOMM40-S/S variant, and to a lesser extent TOMM40-S/VL and TOMM40-VL/VL variants, were the best responders to anti-dementia treatments." (PMID 35330211, 2022). "Moreover, male gender, older age and ApoE-ɛ4 carrier status were independent predictors of the development of dementia in the course of the follow-up period." (PMID 35888143, 2022). "A limitation is that nearly all of the investigations made in this field only consider the influence of APOE on dementia risk and do not examine if this genotype affects exercise behavior." (PMID 36153580, 2022). "Furthermore, treatment trials for hypertension using dementia or cognitive decline as an outcome measure should stratify their results for the APOE genotype." (PMID 35624902, 2022). "Among APOE ε4 non-carriers, we found an association between higher adherence to a healthy dietary pattern and reduced risk of incident dementia." (PMID 34632537, 2022). "MTRNR2L12 expression, which encodes a humanin isoform necessary for neuroprotection and anti-apoptotic function suggested to have utility as a blood marker for cognitive disability and early dementia for adults with Down Syndrome, was very similar to APOE expression." (PMID 35572130, 2022). "In this context, the presence of the APOE ε4 allele has been associated with higher risk of visual hallucinations in PD patients without dementia treated with levodopa." (PMID 35741861, 2022). "Carrying an APOE-ε4 allele (versus not) was associated with a reduction of 7.59 and 7.30 years free of AD and all-cause dementia, respectively." (PMID 35745137, 2022). "Importantly, the APOE ε4 genotype also increases the risk of dementia with Lewy bodies (DLB) and promotes the incidence of dementia in pure synucleinopathies." (PMID 36002891, 2022). "Interestingly, the interaction of APOE ε4 and EN-RAGE for all-cause dementia was statistically significant." (PMID 36085081, 2022). "We could not find other studies that investigated interactions between different dietary patterns and both AD-PRS scores and APOE ε4 status in relation to incident dementia." (PMID 34632537, 2022). "The Apolipoprotein E ε4 (APOE4) genotype is the strongest genetic risk factor for cognitive decline and late onset dementia; yet, when considered in isolation, it accounts for a relatively small portion of population dementia risk." (PMID 36474172, 2022). "We adjusted our models for many well-known riskfactors of dementia: age, high blood pressure, high cholesterol, obesity,diabetes, depression, low education level, and low level of physical activity;only genetic factors such as ApoE were excluded." (PMID 35482013, 2022). "APOE4 is a shared risk factor for both AD and Parkinson’s disease dementia (PDD), and there is evidence for an APOE-genotype effect on multiple aspects of protein aggregation, inflammation, and neurodegeneration across several distinct diseases including AD and PDD." (PMID 35313950, 2022). "The main effects of MIND, GS and APOE on dementia risk were generally confirmed in MAP and WHIMS but not CHAP." (PMID 35807939, 2022). "The objective of this study was to examine long-term associations between amyloid PET, APOE ɛ4, sex, education and cardiovascular/metabolic conditions, and hazard and absolute risk of dementia and mortality in individuals without dementia at enrolment." (PMID 35310829, 2022). "Among genetic backgrounds, the ApoE-ɛ4 allele has long been established as the principal genetic risk factor for dementia, mainly Alzheimer’s disease but also other forms of non-vascular dementia in both homozygous and heterozygous carriers." (PMID 35888143, 2022).
dementia (continued). "First, key risk factors of dementia, such as the level of education and apolipoprotein E genotype were not controlled as they were not available in the HIRA data." (PMID 35986042, 2022). "The apolipoprotein E (ApoE) e4e4 homozygous genotype has been observed to enhance the risk of severe COVID-19, regardless of prior dementia, cardiovascular illness, or type 2." (PMID 35203452, 2022). "When considering the relative associations of cataract extraction, additional education, White race, smoking history, sex, and APOE genotype with dementia risks, the only covariate that was more protective than cataract surgery was not having an APOE e4 allele." (PMID 34870676, 2022). "Lately, APOE genetic mutations have been considered a risk factor for developing dementia in all synucleinopathies subtypes, including PD, but not related to PD onset." (PMID 36153580, 2022). "In contrast, the potential impact of inflammation on the total dementia risk of APOE ε4 non-carriers is relatively high compared to other dementia risk factors." (PMID 36085081, 2022). "APOE ε4/ε4 homozygotes have an almost fivefold higher risk of dementia in comparison to noncarriers, and the cognitive effects of OAB AC use in individuals with this gene have not been clarified." (PMID 36506252, 2022). "Our current results confirm and extend this finding in both all-cause dementia and DVC, within a larger sample of both men and women elderly persons over a long follow-up period, and with further adjustments particularly APOE-ε4 status, cardiovascular, and metabolic diseases and depression." (PMID 35057850, 2022). "Stronger association between glucosamine use and decreased risk of dementia was observed in participants without APOE ε4 carriers." (PMID 36514123, 2022). "Future studies exploring ApoE-ɛ4 patterns might also confirm the possible role of these aspects in the prevention of dementia." (PMID 35888143, 2022). "After adjustment for age, sex, BMI, smoking, blood pressure, and apolipoprotein E (APOE) genotypes, metformin use was associated with 81% lower risk of incident dementia than non-users." (PMID 35455439, 2022). "Sample size, funding source, adjusting for ApoE ε4 status, baseline cognition or education did not significantly modify the association of PA and all-cause dementia." (PMID 35301183, 2022). "Previous studies reported that females are more likely to develop dementia due to carrying APOE ε4, which may be explained by the increased sensitivity of females to Aβ." (PMID 36045363, 2022). "The apolipoprotein E(APOE) as the main carrier regulated the transport and metabolism of cholesterol in the periphery and CNS, and APOE polymorphism was strongly related to neurodegeneration and dementia." (PMID 35740873, 2022). "By contrast, another longitudinal study showed that the association between sleep problems and dementia existed only among non-carriers of the APOE ε4 allele." (PMID 34979998, 2022). "Previous studies investigating markers of SVD and APOE genotype in dementia are scarce." (PMID 35912087, 2022). "However, their results are somewhat hard to compare with ours since we used non-APOE AD-PRSs, and dementia was the outcome." (PMID 34632537, 2022). "A previous study found that neither the family history of dementia nor APOE ε4 status was associated with SCD." (PMID 35983224, 2022). "Participants with incident dementia were often older, male, APOE ε4 carriers, with lower education, higher systolic pressures, a history of diabetes mellitus, anti-hypertensive medication use, former or current smokers, and had a history of stroke or coronary heart disease." (PMID 35965319, 2022). "The APOE genotype ɛ2/ɛ2, school education ≥ 10 years and a BMI ≥ 25 kg/m2 suggested inverse associations with dementia but were not statistically significant." (PMID 36085081, 2022).